CXCL12 (C-X-C motif chemokine ligand 12)
Diseases named in the same sentence as CXCL12 in open-access papers (continued):
Sharing a sentence is not in itself a finding about the gene and the disease.
tumor (continued). "Various chemokines and cytokines promote macrophage recruitment to tumor tissues, such as C-C motif chemokine ligand 2 (CCL2), macrophage colony-stimulating factor (GM-CSF), VEGF, CXCL-12 and hypoxia-inducible factors (HIFs)." (PMID 32850861, 2020). "CXCL12 and IL7R also exhibited significant differences in expression level between normal and tumor tissues (CXCL12: p = 4.47E-36; IL7R: p = 0.037), and between high and low ESTIMATE-scored groups (CXCL12: p = 6.26E-16; IL7R: p = 1.29E-09)." (PMID 33344233, 2020). "For example, cytokines IL-4 and IL-10 secreted by tumor cells or T cells can polarize macrophages to their M2 state in which they are capable of secreting TGF-B1 and CXCL12 to inhibit CD8+ T cell function in support of tumor cell survival and metastasis." (PMID 31979136, 2020). "CXCR4 activation by C-X-C motif chemokine 12 (CXCL12) promotes tumour growth in para and autocrine fashion and fosters tumour cell migration as well as metastatic spread." (PMID 31959787, 2020). "HSF1 signaling in fibroblasts activates a specific tumor-supporting transcriptional program via upregulation of TGF-β and CXCL12, which act both in autocrine and paracrine manner." (PMID 33096815, 2020). "Studies with a neuroblastoma or prostate tumor mouse model showed that high CXCL12 expression in the tumor cells recruited CXCR4-positive monocytes and stimulated the formation of new tumor blood vessels." (PMID 33392074, 2020). "In parallel, the review also addresses CXCL12—that can exert inflammatory and homeostatic activities—and its CXCR4 receptor, due to their major involvement at all stages of tumor progression." (PMID 32582148, 2020). "CXCL12/CXCR4 is the key signaling used to attract and cross-connect multiple cells within the TME aiming for tumor progression and metastasis." (PMID 32260318, 2020). "CAFs secrete multiple angiogenic molecules like VEGF, PDGF, CXCL-12 or HGF that promote ECM remodeling, the proliferation of ECs and the recruitment of ECs and pericytes to the tumor." (PMID 33114328, 2020). "The recruitment of MSCs and their activation into CAFs are stimulated by CXCL-12 and TGF-β secreted by tumor cells." (PMID 33114328, 2020). "Due to the central role in tumour development, a variety of inhibitors of the CXCR4/CXCL12 interaction has been developed during the last decade." (PMID 32019275, 2020). "CXCL12 induces MMP expression in cancer cells and up-regulates the activity of MMPs in tumor microenvironment, which promotes tumor invasion and metastasis." (PMID 33059744, 2020). "The chemokine CXCL12 functions as ligand for CXCR7 too and this other receptor routes on signals that inhibit apoptosis and cooperate to adhesion properties of tumor cells." (PMID 32244473, 2020). "Marked decrease in the B cell compartment from stabilized to progressing tumor was also seen, suggesting that B lymphocytes could have also participated in tumor control through production of antibodies and complement cascade, or recruiting DC through CXCL12 secretion." (PMID 32354143, 2020). "In order to determine the mechanism of neutrophils recruitment into the tumour, we screened neutrophil attracting chemokines (CXCL1, CXCL2, CXCL3, CXCL5, CXCL8 and CXCL12)." (PMID 32778818, 2020). "More recently, the chemokine CXCL12 and its cognate receptors (CXCR4 and CXCR7) have been shown to play central roles in cancer proliferation, angiogenesis, invasion, tumor microenvironment, as well as drug resistance induced by chemotherapy." (PMID 33363463, 2020). "Chemokine axes such as CCL19, CCL21/CCR7, CCL20/CCR6, CXCL12/CXCR4, and CXCL13/CXCR5 correlate with B cell infiltration to tumor sites." (PMID 31991604, 2020). "As a consequence, CAFs release other cytokines, chemokines, growth factors and matrix metalloproteinases (i.e., TGF-β, PGE2, CXCL12, VEGF, MMPs, etc.)that sustain tumor progression, EMT transition and cancer stemness." (PMID 32397392, 2020).
tumor (continued). "HIC1 is expressed in stromal myofibroblasts and regulates CXCL12/SDF1 expression, thereby highlighting a complex interplay mediating the tumor promoting activity of the tumor microenvironment." (PMID 33227080, 2020). "CXCL12/CXCR4 plays an important role in the recruitment of Treg cells into the TME, and contributes to immune suppressive activities and tumor-related inflammation in HCC and malignant pleural mesothelioma." (PMID 31991604, 2020). "Macrophages are attracted to tumor sites expressing chemotactic factors such as CCL2, CCL5, CCL7, CCL8, CXCL1, and CXCL12." (PMID 31991604, 2020). "Homing of MSCs to tumor sites involves a number of cytokines and chemokines, including CCL2, CCL5, CXCL12, secreted by cancer cells." (PMID 32957515, 2020). "It is worth mentioning that although CXCL12 belongs to ELR− chemokine, but it can promote tumor angiogenesis." (PMID 32253815, 2020). "qRT-PCR results showed that the mRNA expression of COL1A1, IGF1, COL5A1, CXCL12, PTEN, and SPP1 were also significantly differently expressed in normal samples and tumor samples." (PMID 32641130, 2020). "Stromal fibroblasts-derived chemokine CXCL12 and Transforming Growth Factor β1 (TGFβ1) induce Src-mediated EMT and proliferate tumor cells present in emboli." (PMID 33414786, 2020). "CAF-derived CXCL12 directly promoted tumor cell EMT and invasion by acting through CXCR4 on tumor cells and downstream activation of the P38 pathway." (PMID 33050580, 2020). "We and others, previously demonstrated that GSCs migrate from the tumor mass toward the SVZ, through the CXCL12/CXCR4 axis or through a pleiotrophin-driven axis." (PMID 33575218, 2020). "In this study, from the perspective of tumor immunity, we identified MMP9, IGF1, CXCL12 and PGF as prognostic differentially expressed IRGs for the first time." (PMID 32675942, 2020). "CAFs secrete TGFβ and SDF-1/CXCL12 that regulate EMT transition and recruit endothelial progenitor cells to the tumor site to facilitate angiogenesis, and tumor growth, respectively." (PMID 32722460, 2020). "Distinct chemokines, in particular CXCL12, CXCL16, and CX3CL, are essential for tumor preservation with their autocrine or paracrine signaling promoting anti-apoptotic effects or proliferation of many tumor types including GBMs." (PMID 32346064, 2020). "At the same time, CXCL12 can attract CXCR4-positive inflammatory, vascular, and stromal cells into the tumor mass to support tumor development." (PMID 33363463, 2020). "Intriguingly, CXCL12/CXCR4 interaction induced mTOR signaling not only influences the immune cells chemotaxis, but also participates in tumor cells migration, such as gastric, pancreatic and renal cancer cells 161-163." (PMID 32483450, 2020). "CXCL12 (SDF-1), ligand of CXCR4, is expressed at the sites of tumor metastasis and is involved in homing of the tumors to different organs." (PMID 32630806, 2020). "Elevated CXCL12 as well as increased tumor metastasis were detected in skeletal tissues, whereas subsequent treatment with CXCR4 antibody decreased tumor spread." (PMID 32585812, 2020). "As for humoral factors, VEGF, macrophage migration inhibitory factor (MIF), IL-6, IL-4/13, IL-10, TGFβ, POSTN, colony-stimulating factor-1 (CSF-1), CCL2, CXCL12, and COX-2/PGE2 directly or indirectly regulate the immunosuppressive tumor microenvironment." (PMID 32707672, 2020). "CXCL12 are small pro-inflammatory chemo-attractant cytokines that bind to a specific receptor CXCR4 with a role in angiogenesis, tumor progression, metastasis, and cell survival." (PMID 33092204, 2020).
tumor (continued). "Overexpression of CXCR4 in anti-EGFRvIII CAR NK cells results in increased chemotaxis toward CXCL12/SDF-1α-secreting glioblastoma cells, complete tumor remission in a number of mice, and increased overall survival." (PMID 33287875, 2020). "For example, the CXCL12/CXCR4 signaling boosts the activity of PI3K and ERK promoting tumor growth and drug resistance in TNBC cells." (PMID 33096815, 2020). "The chemokine SDF-1 (CXCL12), which binds to G protein-coupled receptors CXCR4 and CXCR7, plays an important role in tumor growth and metastasis in different tumor types." (PMID 30874597, 2019). "Further, CXCL12 interaction with its receptor CXCR4, which is key for the homing of the tumor cells to the bone niche, can be disrupted through cleavage of CXCL12 by cathepsin K—the major osteoclast-produced resorptive proteinase." (PMID 31817000, 2019). "The CXCL12/CXCR4 axis is also involved in tumor growth, tumor cell interactions with the microenvironment, vasculogenesis and angiogenesis." (PMID 31507535, 2019). "As the CXCR4 receptor for CXCL12 is expressed on both the tumor cells and EPCs, CAF-produced CXCL12 stimulates tumor growth and neoangiogenesis via acting CXCR4 expressed on these cells." (PMID 31067787, 2019). "Relevant clinical and experimental studies have shown that CXC chemokines, such as the CXCL12 (SDF-1)/CXCR4 axis, can promote tumor growth, invasion and angiogenesis." (PMID 30636642, 2019). "The serum CXCL12 levels in tumour-naïve NSG mice average those of wild type, tumour-naïve Balb/c mice." (PMID 30792442, 2019). "In tumor microenvironment, CXCR4+ MDSCs and neutrophils can be recruited by CXCL12 and they impair the anti-tumor functions of CD8+ cytotoxic T cells leading to increased tumor metastasis." (PMID 30808413, 2019). "With the primary intent to collect circulating tumor cells expressing CXCR4, a new device composed of a commercially available dermal filler, hyaluronic acid based gel (Belotero Intense®), loaded with CXCL12 was realized." (PMID 31332163, 2019). "The stromal fibroblast-produced chemokine CXCL12 primarily binds to the highly expressed CXCR4 receptor on cancer cell surfaces, resulting in the induction of intracellular signaling which lead to tumor progression, angiogenesis, metastasis, and survival." (PMID 31683635, 2019). "Binding of the CXCL12, also called stromal cell-derived factor-1 (SDF-1), to the G-protein coupled receptor CXCR4 mediates a plethora of functions that drive tumor growth and metastasis through chemotaxis, cell survival, proliferation, and angiogenesis." (PMID 31817000, 2019). "The interaction of CXCR4 with its ligand, CXCL12, activates a cascade of cellular signaling promoting the survival, proliferation, adhesion, and migration of the CXCR4-expressing tumor cells." (PMID 31428099, 2019). "In particular, CXCL12 secreted by LECs in the LN SCS contributes to an attractive and supportive metastatic niche for CXCR4+ tumor cells." (PMID 31105685, 2019). "We have recently demonstrated that under pro-inflammatory conditions in the BM, CXCL12 is reduced and HSC hypoxic niches are diluted, allowing gradual leukemogenesis and maintenance of tumor clones." (PMID 30573781, 2019). "As a response, tumour cells interact with CAFs by secreting growth factors (such as FGF-2 and PDGF) and chemokines (such as CXCL12) as well as inducing mechanical stress that eventually leads to CAF activation." (PMID 30944831, 2019). "Increasing evidences demonstrated that CXCL12/CXCR4 promoted EMT and tumor invasion in CRC, miR-133a-3p was markedly downregulated in a variety of cancers and associated with tumorigenesis and metastasis." (PMID 30678736, 2019). "Adding Plerixafor to RTCT blunts treatment-induced increases in CXCL12/CXCR4 signalling, improves primary tumour response and reduces intestinal side effects." (PMID 31239542, 2019).
tumor (continued). "M2 TAMs can produce growth factors and cytokines such as CCL2, CXCL12, CXCR4, TGFβ, VEGF, PDGF, COX-2 and metalloproteinases that determine immunesuppression and stimulate local tumor growth as well as the metastatic process." (PMID 31500586, 2019). "The CXCL12 (SDF-1)/CXCR4/CXCR7 axis, which has been shown to contribute to tumor progression by modulating cancer cell survival, proliferation and migration, also seemed to be involved in the ASC/H295R cell crosstalk." (PMID 31817072, 2019). "During tumor development, cancer cells secrete chemokines such as CCL2, CCL5, CXCL12, and colony stimulating factor 1 (CSF1) to recruit immune cells towards the tumor site." (PMID 31766635, 2019). "Classically, it is dependent on bloodstream-derived monocyte infiltration mediated by CCL2, CCL7, CXCL12, VEGF, and other cytokines produced in the tumor microenvironment by stromal and tumor cells." (PMID 31275860, 2019). "We also investigated the presence of CXCL12, CCL21, CXCL11, IP-10 (or CXCL10), CCL19, and CCL27, which participate to the recruitment of specific NK cell populations to the tumor site." (PMID 31105699, 2019). "The CXCL12/CXCR4 pathway is also involved in vessel co-option, vasculogenesis, fibrosis, lymphocyte trafficking, and cancer cell invasion, depending on the tumor and treatment." (PMID 30800123, 2019). "When close to transformed cells in tumoral ducts, CAF support tumor growth by overexpression of hepatocyte growth factor (HGF), heparin-binding epidermal growth factor (HB-EGF), TGF-β and SDF-1/CXCL12." (PMID 31450710, 2019). "In our data, we identified a switch from MMP1, 3 and 13 in primary tumours to MMP1, 9 and 12 in metastases, as well as a significant upregulation of CXCL12/CXCR4." (PMID 29743718, 2018). "Studies have also shown that the combination of CXCL12 and its receptor CXCR4 can activate NF-κB and increase the secretion of MMP-2 in tumor cells." (PMID 29305742, 2018). "Interestingly, both radiation and chemotherapeutic agents (cyclophosphamide and 5-florouracil) increase CXCL12 expression from the endosteal niche, thus similar anti-cancer treatments in the clinic may enhance the homing of the tumor cells to the bone, and therefore promote bone metastasis." (PMID 29642534, 2018). "Excessive pruning of vessels following anti-VEGF treatment has been reported to associate with increased hypoxia that, through upregulation of CXCL12/CXCR4 axis and HIF1α, supports M2-like TAM, MDSC, and Treg recruitment, thus supporting tumor progression." (PMID 29675018, 2018). "In those studies, CXCL12 overexpression of CXCL12 and its receptor, CXCR4, were found in n = 6 tumor samples." (PMID 29515781, 2018). "High expression of the T cell attracting chemokines CXCL9, CXCL10, CXCL12, and CCL5 correlates positively with CD8+ T cell infiltration across several tumor types, indicating that if the tumors express the proper chemokines, T cells can get there." (PMID 30498499, 2018). "For example, CXCL12 expressing CAFs reduce the effect of anti-CTLA-4 and PD-L1 antagonists in PDAC tumor cells." (PMID 29883428, 2018). "CXCL12 binds to CXCR4 and CXCR7 chemokine receptors, which have important roles in tumor proliferation, metastasis, and angiogenesis, as well as regulation of leukemia stem cell migration." (PMID 29301363, 2018). "The migration and the invasion processes of tumor cells can be regulated by many factors, such as BRMS1, E-cadherin, CXCL12, MMP9, Orai1, Stim1, TGF-β, and VEGF." (PMID 29316690, 2018). "In a mouse model of PDAC, fibroblast activating protein-expressing CAFs produce CXCL12 that coats tumor cells and prevents CXCR4+ CD8+ T cells from infiltrating tumor nests and controlling the tumor." (PMID 30498499, 2018). "Several studies have shown that another chemokine, CXCL12, facilitates lymphatic metastasis of CXCR4+ tumor cells." (PMID 29527513, 2018).
tumor (continued). "The expression of CXCL12 mRNA was higher in rectal location (p = 0.04) with a tendency to be higher in later stages (p = 0.15), while the expression of CXCR4 was lower in tumours with a lymphatic invasion (p = 0.02), compared to their counterparts." (PMID 29887884, 2018). "Mɸ are recruited into irradiated tumour tissue at both acute and late stages through Mø/Mɸ chemoattractants CCL2, CCL5, CCL7, CCL8, CXCL12, VEGF and CSF-1." (PMID 30178305, 2018). "Chemokine axes, such as fractalkine (CX3CL1)/CX3CR1, C-X-C motif chemokine ligand 12 (CXCL12)/C-X-C chemokine receptor type 4 and 7(CXCR4/CXCR7), CCL2/CCR2, and CCL5/CCR5, are clearly involved in tumor progression." (PMID 30123112, 2018). "High CXCR4 expressing tumor cells have a greater invasive and metastatic potential, and CXCR4+ cells migrate following a concentration gradient of CXCL12." (PMID 30564115, 2018). "High levels of CXCL12 in organs and tissues, such as lymph nodes, lung, liver, and bone/bone marrow (BM), are thought to direct the metastasis of CXCR4-expressing tumor cells." (PMID 30191351, 2018). "For instance, reactive astrocytosis as a result of surgical resection can promote tumor cell invasion via the secretion of distinct paracrine factors (e.g. TGF-α, CXCL12, S1P, GDNF, MMP-2, MMP-9)." (PMID 29728948, 2018). "The combination of chemokine CXCL12 and its receptor CXCR4 can up-regulate the expressions of MMP-2 and MMP-9 in tumor cells and reduce the secretion of tissue inhibitor of metalloproteinases (TIMPs)." (PMID 29305742, 2018). "The interaction of CXCL12 and CXCR4 has been addressed as engaging in the tumour progression of various cancers, including CRC." (PMID 29887884, 2018). "Monocytic MDSCs, that include macrophages at different maturation stages, express CCR2, CXCR2 and CXCR4, and can reach the tumor via their specific ligands CCL2, CXCL5 and CXCL12 respectively." (PMID 30319638, 2018). "Diverse chemokines, i.e., CCL2 (MCP-1), CCL5 (RANTES), CCL7 (MCP-3), CXCL8 (IL-8), and CXCL12 (SDF1), released by tumor cells induce migration, differentiation, and survival of tumor-infiltrating myeloid cells." (PMID 29686671, 2018). "High expression of the CCL5 and CXCL12 genes in Lauren’s diffuse type of GC and increased expression of ADAMTS1, CXCL12, and CCL19 genes were found in peritoneal metastasis, suggesting their involvement in tumor progression." (PMID 29772686, 2018). "Through binding to CXCL12, NOX-A12 inhibits signaling on both its receptors, CXCR4 and CXCR7, thus preventing angiogenesis as well as tumor cell proliferation, invasion, and metastasis." (PMID 29562664, 2018). "Focusing on CXCL12, CCL2, and CCL22, all three chemokines aid tumor development and progression by recruiting immune suppressive cell subsets." (PMID 30126117, 2018). "When the Chemokine C-X-C Motif Receptor Type 4 (CXCR4), whose expression can be enhanced by hypoxia, binds Stromal Cell-derived Factor 1 (CXCL12), secreted by CAFs, release of MMP-9 to the tumour microenvironment is stimulated." (PMID 29743718, 2018). "We showed that E5 improved the efficacy of multiple chemotherapeutics in mice bearing breast cancer tumors (4T1) by inhibiting tumor angiogenesis and tumor cell adhesion to stromal cells by blocking the CXCR4/CXCL12 axis." (PMID 29263923, 2017). "CAFs also secrete factors including VEGF, CXCL12, FGF, IL-8/CXCL8 and PDGF to stimulate tumor angiogenesis, CAFs release factors such as HGF, CCL5 and stanniocalcin 1 (STC1) to stimulate tumor invasiveness and metastasis." (PMID 29383119, 2017). "CXCL12 and CXCL3L1 Chemokines are key factors for NK migration to tumor sites, and play a significant role in the tumor immunosurveillance." (PMID 29450136, 2017). "Endogenous cyclin D1 maintained abundance of stromal cell-derived factor 1 (SDF-1α), also called CXCL12, which plays a central role in the promotion of tumor growth and angiogenesis." (PMID 29137220, 2017).